MYC (MYC proto-oncogene, bHLH transcription factor)
Diseases named in the same sentence as MYC in open-access papers (continued):
Sharing a sentence is not in itself a finding about the gene and the disease.
cancer (continued). "c-MYC, ‘‘the oncogene from hell’’, is associated with more than half of all human cancers." (PMID 35008356, 2021). "MYC oncogenes (c-, L-, and N-) encode a family of related transcription factors that are overexpressed in a majority of cancers and responsible for ~100,000 cancer-related deaths in the United States each year." (PMID 33416496, 2021). "Similarly potent alterations in cancer-associated genes, e.g., MYC amplification (neuroblastoma), SMARCB1 deletion (malignant rhaboid tumor), BRD4-NUT fusion and EWSR1 fusions also profoundly affect gene expression." (PMID 34502326, 2021). "The MYC oncogene encodes a transcription factor that triggers gene expression in cancer cells." (PMID 34783629, 2021). "Enhanced MYC levels in tumors induce the “squelching” of SPT5, subtracting this and other components of elongation machinery from genes that are known targets of MYC-dependent repression, such as those encoding TGFβ pathway proteins and regulators of immune system in cancer." (PMID 33801599, 2021). "The MYC gene encodes a transcription factor that plays multiple roles in cancer transformation." (PMID 32722129, 2020). "Aberrant MYC expression is frequently associated with cancer cell vulnerability and poor prognosis." (PMID 32724061, 2020). "Interestingly, their expression correlates with a cancer-associated single nucleotide polymorphism (SNP), the rs6983267, which is located in a super-enhancer around the transcription start site of the MYC gene at 8q24." (PMID 33142861, 2020). "Indeed, the strong oncogenic roles of MYC depend on causing the aberrant expression of target genes to enhance cancer cell growth and cell progression 17,24." (PMID 32284755, 2020). "This phylostratic effect induced by the oncogenic potency of c-MYC linked to induced polyploidy, metabolic stemness, and bivalency likely creates the evolutionary “cancer attractor” postulated by Kauffman as situated close to the summit of metaphoric Waddington Hill of the development potential." (PMID 33228223, 2020). "In the context of cancer, it is important to determine whether AGO1 loss of function alters MYC-dependent cancer progression and vice versa." (PMID 32527935, 2020). "The c-MYC oncogene is associated with cell growth, proliferation and a range of malignant tumours." (PMID 33047051, 2020). "Dysregulation of c-MYC causes cancer when caspase activity is disrupted." (PMID 33551748, 2020). "Furthermore, MYC activation in cancer cells is associated with an enhanced expression of the microRNA miR-105, which is reported to destroy vascular endothelial barriers in order to promote cancer progression and metastasis." (PMID 33081056, 2020). "The most frequent MYC mutations associated with cancer are located in the codons for Thr58 and Pro59 in the NH2-terminal transactivation domain, with such mutations having been shown to stabilize c-Myc by preventing its degradation by the ubiquitin-proteasome system." (PMID 32429232, 2020). "For instance, many cancers are caused by dysregulation of the MYC oncogene, hence our finding of a new regulator of MYC may potentially lead to new therapies." (PMID 32843692, 2020). "Alterations in MYC oncogene are a hallmark of many human cancers." (PMID 32310340, 2020). "In the 8q area is the gene MYC, described to be associated with cancers in the COSMIC database." (PMID 33400739, 2020). "MYC dysregulation occurs in various cancer types and is associated with more aggressive tumors." (PMID 32850316, 2020). "Moreover, lncRNA PVT1 shares a recognized cancer risk locus with the nearby, well-known MYC oncogene." (PMID 30925926, 2019).
cancer (continued). "YBX1 has also been linked to the expression of other cancer-related genes (e.g., c-MYC, CCND1)." (PMID 31461477, 2019). "Importantly, re-activation of MYC mRNA expression has been implicated as an acquired resistance mechanism to BET bromodomain inhibition in several cancer types, demonstrating MYC’s importance." (PMID 30846826, 2019). "Therefore, it is possible that p300 inhibitors exhibit a synthetic lethal anticancer effect in CREBBP-deficient cancer cells by inhibiting the expression of MYC." (PMID 31590683, 2019). "Furthermore, copy numbers of the lincRNA PVT1 are increased in more than 98% of cancers that have increased copy numbers of MYC, and high expression levels of PVT1 are associated with a poor prognosis in various cancer patients." (PMID 31801944, 2019). "Besides cancer, the proto-oncogene MYC is also linked to various developmental defects including common congenital malfunction, cleft lip with or without cleft palate (CL/P)." (PMID 31724731, 2019). "Moreover, GWAS also indicated that PVT1 and MYC located in the 8q24 segment are associated with cancer risk." (PMID 31309249, 2019). "Our data may show a common underlying epigenetic dysregulation in cancer associated with broad enrichment of repressive chromatin marks and aberrant DNA hypermethylation at TSSs in combination with MYC network activation." (PMID 31097695, 2019). "Interestingly, cancer-associated MYC translocations can lead to UTR truncations that delete predicted motifs: potentially impacting function and contributing to MYC dysregulation." (PMID 31206539, 2019). "MYC is also a driver of genomic instability, another hallmark of cancer." (PMID 31455158, 2019). "In pluripotent stem cells and cancer, suppression of lysosomal and autophagic function is directly downstream of c-MYC overexpression and may represent a hallmark of malignant transformation." (PMID 31399583, 2019). "Moreover, MYC targets V1 group of proteins are specifically associated with cancer cells with a fast rate of cell division 22, and MYC is an oncogene, uncontrolled expression of which is associated with a wide range of human cancer." (PMID 30280445, 2019). "Deregulated expression of c-MYC has been implicated in progression of many types of cancer." (PMID 30836996, 2019). "Finally, by applying a comparative oncogenomics strategy to uncover additional culprits of tumorigenesis, we identified MCL1 as a druggable cancer driver that collaborates with MYC in BRCA1-deficient TNBC." (PMID 30674894, 2019). "In addition, MYC family members play crucial roles in stem cell biology, and MYC-dependent metabolic reprogramming is tightly related to regulation of CD44-variant-dependent redox-stress in cancer stem cells." (PMID 31088567, 2019). "In addition, some cancer-causing molecules are transcriptionally repressed by ERβ, including the MYC oncogene." (PMID 30979864, 2019). "Furthermore, it has been shown that the MYC allele in cis linked to the cancer risk-associated SNP variant shows significantly higher expression than the MYC allele linked to the nonrisk-associated variant." (PMID 31309249, 2019). "They modulate MYC expression to prevent cancers caused by overexpression of the gene." (PMID 30871121, 2019). "Evidences from both Drosophila and human cancer cell lines show that a large number of snoRNAs are downregulated upon the depletion of the MYC oncogene and that several snoRNA host genes or genes encoding for snoRNPs feature MYC binding sites in their promoter sequences." (PMID 31533350, 2019).
cancer (continued). "Given that MYC deregulation is a hallmark of many cancers, we hypothesize that at least some of these events are caused by derepression of MYC via the RBM25−BIN1−MYC pathway." (PMID 30635567, 2019). "For example, copy number amplification of the oncogene MYC has been found in most types of cancer; copy number loss of the tumor suppressor APC may lead to increased nuclear functional β-catenin protein in OS." (PMID 30613366, 2018). "Therefore, our study suggests that the MYC-mediated sensitivity of KRAS-mutated cancer cells to BET inhibition is highly context dependent and that such effectivity relies on more than one molecular mechanism." (PMID 29721157, 2018). "However, cancer associated genes seem to be selectively dependent on BRD4 being c-MYC the paradigm of this model." (PMID 30466442, 2018). "Therefore, misregulation of apoptotic pathways has an important role in cancer development, because mutations or amplifications in the oncogenes (e.g., MYC) can compromise apoptotic pathways." (PMID 29371588, 2018). "In cancer cells, disruption of ribosome biogenesis and protein synthesis is associated with altered expression of key genes encoding translation initiation factors and proto-oncogenes such as mTOR, c-MYC, and RAS61–63." (PMID 29674660, 2018). "Interestingly, here we showed that NANOG and c-MYC expression, as stemness-associated factors, were detected in these OCSCs and that their cancer stem-like properties were negatively regulated by STON2 expression." (PMID 30518424, 2018). "Although mechanisms linking inflammatory colitis to CRC are incompletely understood, these cancers may also show activation of Wnt signaling, including activating β-catenin mutations, or amplification of c-MYC." (PMID 29346117, 2018). "Expression of mutant FGFR3 in MEFs also caused a moderate increase in basal MYC levels, and MYC’s well-described oncogenic activities may be important in FGFR3-dependent cancers." (PMID 29423038, 2018). "Importantly, selected genes from the MNP300 panel are highly expressed in the three examined cancer cell lines compared to normal fibroblasts, suggesting involvement of MYC association with the NuA4 complex in activation of the MNP300 panel in cancer cells." (PMID 30108681, 2018). "We used a genetic model which, through a combination of the UAS-Gal4 and Flp-FRP binary systems, allowed us to express MYC in the P compartment and to induce second mutations of interest later in time, so reproducing the temporal sequence that is likely to occur during cancer initiation." (PMID 30619451, 2018). "However, while the successful employment of these drugs is moving faster from selected MYC-addicted hematological malignancies to solid cancers, questions about cancer specific susceptibility to these drugs still remain." (PMID 30466442, 2018). "A continuous study to identify the distinct mechanism of cell death mediated by the CLK inhibitor as well as its key downstream targets may demonstrate the mechanism underlying MYC induction‐mediated cancer cell vulnerability to CLK inhibition." (PMID 29769258, 2018). "Interestingly, in the analysis of microarray results in a GEO database, we found that the expression level of DEPTOR is associated with MYC in several types of cancer." (PMID 29472861, 2018). "Indeed, point mutations in the MYC coding sequence in the context of cancer tend to cluster at the T58 phosphorylation site within the MYC transactivation domain." (PMID 28398229, 2017). "MYC oncogene family members are broadly implicated in human cancers." (PMID 28424416, 2017). "Elevated ODC expression is often linked with increased MYC activity in cancers." (PMID 29240775, 2017).
cancer (continued). "MYC is widely known as an oncogene and the expression of genes encoding mitoribosomal proteins, mitoribosome assembly factors and mitochondrial translation factors is modified in numerous cancers." (PMID 29132502, 2017). "Furthermore, inhibition of MYC almost invariably causes growth arrest of cancer cells both in culture and in vivo." (PMID 28583252, 2017). "c-MYC is associated with more than more than 70% of cancers." (PMID 28422055, 2017). "However, presumably because of ectopically carrying the MYC allele, iPS cells share several cellular properties with cancer cells naturally overexpressing MYC, such as malfunctioned senescence and cellular immortality." (PMID 28590415, 2017). "Thus far, targeting chromatin modifiers associated with MYC’s oncogenic function in cancer has proven successful and effective; however, there is still much progress to be made to improve inhibitors as well as clinical efficacy for patients." (PMID 28505071, 2017). "Expression of both panels of genes is increased in three cancer cell lines examined compared to HS68 cells, suggesting that expression of both panels of genes in cancer may involve MYC association with the NuA4 complex." (PMID 29321817, 2017). "MYC is inferred as a major player in metabolic transformation of cancer cells due to its pervasive impact on the genes encoding protein and enzyme mediators of glycolysis, glutaminolysis, mitochondrial biogenesis, and biosynthesis of macromolecules (Stine, Cairns, Kress)." (PMID 28443281, 2017). "Given the conserved nature of the FIR-XPB interaction, we would predict impaired Pol II pausing and defective transcriptional repression of MYC might contribute to hyperproliferation and cancer associated with XPB-related human diseases." (PMID 28398229, 2017). "The dependency of MYC expression levels on E6/E7 may provide a functional link between the viral oncogenes and these important cancer-linked metabolic circuits in HeLa cells, an issue that deserves further exploration." (PMID 29290953, 2017). "Together, these studies produce contrasting predictions, one where HUWE1 may drive cancer via activation of MYC function and one where loss of HUWE1 would promote cancer by increasing levels of MYC, DNA damage and genomic instability." (PMID 28003334, 2017). "The region around the MYC gene carries inherited risk towards multiple major forms of cancer." (PMID 28583252, 2017). "MYC’s capacity to promote growth and cell division is essential for tissue patterning during organ growth and, given that elevated MYC is inexorably linked to cancer initiation and progression, developmental signals must normally ensure tight control of MYC expression." (PMID 28398229, 2017). "In this pathway, TCF4, also called TCF7L2, forms a complex with beta-catenin, and the beta-catenin–TCF4 transcription factor complex binds preferentially to the cancer risk-associated rs6983267 (G) allele in vivo and in vitro leading to a two-fold change in c-MYC expression." (PMID 29232378, 2017). "However, the expression of MYC appears more significantly associated to the presence of carcinoma compared to benign tissue, than to the aggressiveness of the tumors according to this dataset." (PMID 28938627, 2017). "High MYC expression is linked to proliferative activity in most normal tissues and in cancer." (PMID 29527532, 2016). "Notably, MYC gain-of-function mutations can enhance the proliferation of cancer cells, the metastasis of cancers, and instability of the genome." (PMID 27689328, 2016). "However, c-MYC (and other members of its family) is rarely mutated in cancers but is activated by gene amplification or translocation, and the resulting abundance of c-MYC activity leads to cellular immortality associated with blockade of differentiation." (PMID 27655693, 2016).
cancer (continued). "Cancers defined by mutations in FBW7 (which disrupt the association of FBW7 with the CPD-client protein) are characterized by elevated levels of the CPD-client oncoproteins MYC, c-Jun, cyclin E and NOTCH." (PMID 27438153, 2016). "MYC is one of the most commonly deregulated oncogenes in human cancers and the mapping of multiple cancer risk loci and regions of focal amplification to MYC enhancer regions provides strong evidence that inappropriate MYC expression can result from the perturbation of long-range control." (PMID 27490482, 2016). "VEGF, which has the ability to increase vascular permeability, may play a central role in c-MYC-induced cancer-associated ascites." (PMID 27483433, 2016). "MYC has also been found to be implicated in various biological phenomena and diseases such as healthy life span, Alzheimer's disease, Huntington disease, Parkinson disease and cancer." (PMID 26003165, 2015). "In support of these findings, treatment with ART down-regulated the expression of multiple molecules associated with maintaining cancer stemness and metastatic potential, including c-MYC, epidermal growth factor receptor (EGFR), c-MET, Src, and focal adhesion kinase (FAK)." (PMID 26426994, 2015). "Cancers with a c-MYC GCN gain are often associated with a poor prognosis." (PMID 26426996, 2015). "Similarly, the emerging variety of interactions between lncRNAs and MYC, a well-known oncogenic transcription factor linked to most types of cancer, have caught the attention of many biomedical researchers." (PMID 27077133, 2015). "Moreover, PVT1 lies in a recognized cancer risk locus that it shares with the well-known MYC oncogene." (PMID 25883951, 2015). "One gene that is frequently mutated in many cancers encodes a protein called MYC." (PMID 26083714, 2015). "In addition, other transcription factors have been associated with poor prognosis in PCa, amongst which c-Myc (MYC) is a well-established oncogene in many other cancers." (PMID 25869206, 2015). "High level MYC expression is associated with almost all human cancers." (PMID 24466310, 2014). "Increased proliferation may provide yet another alternative explanation for increased MYC expression in CNS DLBCL, as MYC expression has been shown to be closely linked to the cell cycle and is part of the “proliferation signature” in a variety of cancers." (PMID 25479599, 2014). "Besides translocation, MYC can undergo oncogenic deregulation via high-level gene amplification as well as mutations in cis-regulatory elements in several cancer types (e.g., myeloma, colon carcinoma and neuroblastoma)." (PMID 24466310, 2014). "Most of these genes belong to several cancer-associated genes such as MYC and BRCA1." (PMID 22615874, 2012). "While enhanced methylation (and in likelihood, transcription silencing) of these differentiation-associated genes is consistent with the cancer phenotype, we also observed several proto-oncogenic TFs in this group, including MYC and TCF, PAX, and RUNX family genes." (PMID 22412954, 2012). "In addition, we have compared our MYC target genes with MYC targets in three cancer cell lines identified by ENCODE ChIP-seq data." (PMID 22039435, 2011). "Since MYC is responsible for regulating many other genes, irregular expression of MYC has been linked to several cancers, and some studies have identified this gene as a potential cancer drug target in humans." (PMID 22479706, 2011). "For instance, in the ‘gene expression, cancer and cell morphology’ network, miR-218 may target genes directly and indirectly linked to two oncogenes, MYC and SRC." (PMID 20838434, 2010).